GSDMD (gasdermin D)
Diseases named in the same sentence as GSDMD in open-access papers (continued):
Sharing a sentence is not in itself a finding about the gene and the disease.
tumor (continued). "Meanwhile, pyroptosis of tumour cells results in the activation of the caspase-1/GSDMD pathway in macrophages to release some proinflammatory cytokines, such as IL­6 and IL­1, and then triggers cytokine release syndrome (CRS)." (PMID 35896522, 2022). "Remarkably, activation of endoplasmic-reticulum (ER) stress induced by GSDMD promotes cell apoptosis during cisplatin chemotherapy, thereby increasing the treatment sensitivity of tumours." (PMID 35289335, 2022). "Taken together, we concluded that genetically modified tumor cells with inducible GSDMD-NT overexpression demonstrated full ICD characteristics, with potential to be explored as a new tumor cell vaccine." (PMID 36189310, 2022). "GSDMD -mediated tumor-cell pyroptosis also stimulates anti-tumor immune response and promotes tumor immunosuppression in immunocompetent mice." (PMID 36323669, 2022). "GSDMD depletion partially rescues the growth defects of Mll4−/− B16 tumor cells in immune-competent mice and mitigates the survival benefits conferred by Mll4 ablation." (PMID 36323669, 2022). "Then, a TUNEL staining was performed to analyze the pyroptotic cells in tumor tissues, and a specific labeled antibody was used to mark the expression of GSDMD molecules, and both of them were induced by doxy treatment." (PMID 36189310, 2022). "A significant increase in TME immune cells was detected in GSDMD high-expressed tumor, compared to GSDMD low-expressed tumors." (PMID 35274175, 2022). "NLRP3/Caspase-1/IL-1β signaling axis within the tumor-infiltrating mononuclear phagocytes promotes tumor growth in GSDMD independent manner in vivo." (PMID 36439171, 2022). "There are also many studies on GSDMD in tumor treatment, and it is often regarded as a tumor suppressor gene that plays a role in tumor cells." (PMID 36569221, 2022). "Typically, negatively charged free GSDMD proteins or protein cages are hard to transport into tumor cells to initiate pyroptosis." (PMID 36280674, 2022). "Taken together, these data indicate that GSDMD-mediated pyroptosis enhances tumor immunity and promotes tumor immunosuppression in both murine and a variety of human cancers." (PMID 36323669, 2022). "The findings from the UALCAN database revealed that the expression of all six GSDMs based on the tumor stage in LUAD was increased (particularly GSDMD)." (PMID 36505798, 2022). "Low expression was found in GSDMD in GC cell lines and models, additionally explorations have shown that down-regulation of GSDMD is capable of regulating the expression of cellular cycle-related proteins and promote tumor cell growth." (PMID 35153782, 2022). "Data from the immunohistochemical staining of paraffin sections and RT-qPCR of RNA from frozen specimens showed that the expression of GSDMD in tumour tissues was significantly higher than that in adjacent tissues." (PMID 35289335, 2022). "Future studies are warranted to determine if the induced inflammatory caspases or murine granzymes mediate GSDMD cleavage and pyroptotic induction in Mll4−/− tumor cells." (PMID 36323669, 2022). "In this study, we developed a new and commonly applicable approach to induce pyroptosis of tumor cells through transgenic modification of the GSDMD-NT gene." (PMID 36189310, 2022). "Here, we report that GSDMD, previously reported mainly as a pyroptosis effector, is highly expressed in tumours and enhances cisplatin-induced apoptosis." (PMID 35289335, 2022). "In this work, to leverage Gasdermin-triggered pyroptosis for antitumor immunotherapy, we develop an intracellular bacterium—attenuated Salmonella typhimurium (VNP) delivery system to shuttle Gasdermin D protein to initiate the tumor cell pyroptosis." (PMID 36280674, 2022). "The use of a PERK inhibitor reduced the cisplatin-induced decreases in the volume and weight of transplanted tumours in both the GSDMD-overexpression group and the control group." (PMID 35289335, 2022).
tumor (continued). "By using fresh frozen samples of tumor and paired tumor-adjacent normal tissues from our institution, we found that NEK7 and GSDMD were significantly upregulated in tumor tissues compared to normal tissues." (PMID 35223495, 2022). "In other investigations, GSDMA, GSDMB, GSDMC, and GSDMD have also been shown to have tumor-suppressing properties." (PMID 35769504, 2022). "The IC50 results showed that overexpression of GSDMD significantly increased the cisplatin sensitivity of tumour cells." (PMID 35289335, 2022). "In this study, it was found that multiple pattern-recognition receptors are underexpressed in tumour cells, making it difficult to activate pyroptosis in tumour cells even if GSDMD is highly expressed." (PMID 35289335, 2022). "In detail, IL-1β and IL-18 are released through the first activated Gzm B/caspase-3/GSDME pathway in target tumor cells, which later amplifies the inflammatory response by activating the caspase-1/GSDMD axis in MΦs." (PMID 36482419, 2022). "Both GSDMD and GSDME have been focused in the field of tumor-targeted therapy, and several small molecule agents or nano-drugs targeting GSDMD and GSDME have been developed." (PMID 35739593, 2022). "At the beginning of the study, we demonstrated that overexpression of GSDMD-NT had the capacity to induce pyroptosis in multiple tumor cell lines, including TC-1, 4T1, and CT26." (PMID 36189310, 2022). "Our results indicated that the expressions of GSDM family genes, particularly GSDMD, were significantly positively correlated with the immune score and negatively correlated with the RNA or DNA stemness score and tumor purity in various cancer types." (PMID 36003332, 2022). "The other paper reported that the higher expression of pyroptosis signaling pathway effectors caspase-1, IL-1beta, and GSDMD was negatively related to tumor size and lymph node metastasis." (PMID 34381023, 2021). "As for the tumor grade, GSDMD and GSDME expression increased gradually and significantly from grade 1 to grade 4." (PMID 34731088, 2021). "One study revealed that high GSDMD expression was positively correlated with larger tumor size, advanced TNM stages and also poor prognosis in LUAD." (PMID 34830775, 2021). "Pyroptosis-related genes (PRGs), such as NLRP3, Caspase 1 (CASP1), Gasdermin D (GSDMD) and Gasdermin E (GSDME), are strongly implicated in oncogenesis and tumor progression." (PMID 34488540, 2021). "The NLRP3/Caspaseaspase-1/GSDMD pathway has been reported to be crucial for NLRP3 induced tumor progression." (PMID 34393801, 2021). "Intriguingly, these tumor cells were indeed found to express not only GSDMD, but also the upstream NLRP3-inflammasome components, akin to myeloid cells, and to display spontaneous signs of inflammasome activation and IL-1β production." (PMID 34490126, 2021). "This is not the case in patients with LUSC, highlighting the differential role of GSDMD in different tumor contexts." (PMID 34490126, 2021). "Treatment with CD147 recombinant protein (BP4745, BOSTER) in RT4 cells, which is a relatively low-grade malignant cell line, significantly contributed to GSDMD expression, leading to increased tumor proliferation as characterized by Ki-67 expression." (PMID 32149134, 2020). "In some regions identified by DMRs or FL analysis, mapped genes are known to act as tumor suppressors such as the GSDMD and HOXA5 genes." (PMID 30940212, 2019). "The high expression of GSDMD was related to larger tumor size, late tumor-node-metastasis (TNM) stages, and lower survival rate." (PMID 31616642, 2019). "Immunofluorescence (IF) analysis of tumor tissues from two mice per group on Day 1 revealed elevated c‐Cas1 levels and increased N‐GSDMD expression in G4 tumors, validating pyroptosis activation through the canonical c‐Cas1/GSDMD axis." (PMID 40847518, 2026). "A positive correlation was observed between GSDMD level and tumor size (R = 0.332; p = 0.01)." (PMID 41977007, 2026).
tumor (continued). "Mechanistically, ILC1s characterized by high GZMA/GZMB expression represent the primary subset accumulating within tumors and are responsible for enhancing antitumor immunity, which can induce Gasdermin D cleavage in tumor cells to initiate tumor pyroptosis for a cascade of cancer-immunity cycle." (PMID 41998137, 2026). "GSDMD is the most commonly used factor in tumor pyroptosis studies." (PMID 40756987, 2025). "In contrast, GSDMD activation was infrequently observed in tumor cells." (PMID 40759573, 2025). "Additionally, viral therapies such as the oncolytic adenovirus H101 induce endothelial pyroptosis via caspase-1/GSDMD activation, synergizing with anti-PD-L1 therapy to suppress tumor growth." (PMID 41235238, 2025). "Immunofluorescence staining for cleaved-caspase-1 and GSDMD was employed to assess the killing effect of M@P on tumors, confirming that M@P could promote pyroptosis in tumor cells." (PMID 39743555, 2025). "GZMA+CD8+ T cells promote pyroptosis of tumor cells via GSDMD." (PMID 40924501, 2025). "Thus, DSF treatment targets GSDMD activation particularly in immune cells, leading to tumor progression." (PMID 40759573, 2025). "On one hand, activating the GSDMD signaling pathway effectively suppresses tumor growth; on the other hand, pyroptosis may paradoxically promote tumor cell migration and metastasis." (PMID 39994107, 2025). "First, GSDMD-mediated pyroptosis exhibits tumor-suppressive effects by triggering immunogenic cell death, yet excessive inflammation from sustained pyroptosis may conversely foster pro-tumorigenic microenvironments." (PMID 40491921, 2025). "Of note, knockdown of GSDMD confined tumor growth both in vitro and in vivo." (PMID 41291696, 2025). "Aligning with our results, recent studies have reported that natural compounds, such as Reniformin A, Cinobufotalin, Omega-3 docosahexaenoic acid, metformin, and anthocyanin, induce tumor regression via the induction of GSDMD-mediated pyroptosis in various cancers." (PMID 40898252, 2025). "In non-tumor diseases, elevated GSDMD expression exacerbates tissue inflammation." (PMID 39994107, 2025). "Similarly, elevated GSDMD expression in endometrial cancer correlates with improved anti-tumor immune responses and a more favorable prognosis." (PMID 40691738, 2025). "Tumor growth can be influenced by GSDMD, alongside IL-1 family members." (PMID 40141358, 2025). "GSDMD also mediates immunosuppression in the inflammatory tumor microenvironment (TIME)." (PMID 39994107, 2025). "In colon cancer, GSDMD is activated in tumor cells through the ROS/ caspase-1 signaling pathway." (PMID 39994107, 2025). "Additionally, ZIF-8 nanoparticles induce pyroptosis in 4T1 cells via a caspase-1- GSDMD-dependent pathway, which activates antitumor immunity and reprograms the immunosuppressive tumor microenvironment, leading to effective tumor inhibition." (PMID 39994107, 2025). "Public data analyses suggest that the infiltration levels of CAFs in tumor tissues are positively correlated with GSDMD and GSDME expression in malignant cells, implying that CAFs may mediate pyroptosis in tumor cells through specific molecular crosstalk." (PMID 40755775, 2025). "Syngeneic graft experiments with MC38 cells overexpressing YY2 showed that BUB1B knockdown abolished the YY2 tumor suppressive effect, as well as its positive impact on chromosome missegregation, caspase‐1/GSDMD activation, IL‐1β, and cell death rate in syngeneic graft lesions." (PMID 39903759, 2025). "Considering the finding that tumor cell–derived factors suppressed caspase-8 and GSDMD activation in CD4+ T cells, it will be intriguing to identify and characterize these factors in the TME, which could be potential new targets for cancer immunotherapy." (PMID 40759573, 2025). "For instance, GSDMD mediates tumor cell resistance in hypoxic environments." (PMID 39994107, 2025).
tumor (continued). "Furthermore, H2 diffusion to mitochondria induces an oxidative stress response, triggering pyroptosis through the canonical ROS/caspase-1/GSDMD pathway, enhancing tumor immunogenicity and activating T cell-mediated adaptive immune responses." (PMID 41402300, 2025). "Similarly, ZIF-8 nanoparticles induce pyroptosis through a caspase-1- GSDMD-dependent pathway, triggering a tumor immune response and reprogramming the tumor's immunosuppressive microenvironment (TME) to effectively inhibit tumor growth." (PMID 39994107, 2025). "Notably, SNRPE targeting was unable to enhance the expression level of cleaved-GSDMD in tumor cells treated with NAC." (PMID 40386046, 2025). "As the abnormal upregulation of GSDMD in OSCC after cisplatin chemotherapy induces tumor metastasis, targeted regulation of GSDMD expression may be an effective strategy for inhibiting postchemotherapy OSCC metastasis." (PMID 40178046, 2025). "We reason that this could be due to the observed accumulation of aggregated CHMP2A and CHMP4B proteins, members of the ESCRT membrane repair machinery, in the membrane of both human and mouse CRC tumor cells, that were decreased upon ablation of GSDMD in mice." (PMID 38898209, 2024). "PCR results revealed a significant increase in the mRNA expression levels of caspase-1, caspase-11, NLRP3, and GSDMD in the transplanted tumor tissues when LINC00365 was downregulated, and western blot analysis revealed a significant increase in the expression of the corresponding proteins." (PMID 39439418, 2024). "We further sought to confirm whether PA-induced cleavage of GSDME, including other gasdermin family proteins GSDMC and GSDMD, which have received much attention in tumor research." (PMID 39138191, 2024). "In agreement with the upregulation of MHC, we also observed a strong enrichment in interferon signaling for effective tumor-suppressing treatments, particularly for NT GSDMD + IL-12, as well as for ineffective NT GSDMD + IL-1β + IL-18 treatment, although not necessarily with the same genes." (PMID 39737979, 2024). "Furthermore, mRNA-LNP technology is also used to directly deliver mRNA-encoded therapeutic proteins such as GSDMD and TRAIL to tumors, inducing tumor cell death and exploring new avenues for treatment." (PMID 39203999, 2024). "Additionally, genes, associated with inflammasome and cell death including tumor suppressive TNF signaling pathways were upregulated in the samples treated with NT GSDMD + IL-1β + IL-18." (PMID 39737979, 2024). "Above all, the canonical inflammasome pathway in CRC is characterized by the formation of inflammasomes and activation of caspases, as well as subsequent cleavage of GSDMD, resulting in cell pyroptosis and inflammatory responses which finally lead to tumor suppression." (PMID 39062587, 2024). "Taken together, this data suggests that the role of GSDMD in cancer may vary according to the tumor type and is context-dependent." (PMID 39224600, 2024). "The tumor-promoting role of GSDMD in sporadic CRC also suggests that tumor cells may be protected against GSDMD pore formation and subsequent pyroptosis." (PMID 38898209, 2024). "Collectively, GSDMD-mediated pyroptosis has an important anti-tumor role in CRC." (PMID 39062587, 2024). "This pro-tumor function may be attributed to the release of inflammatory cytokines, such as IL-1β, following GSDMD pore formation." (PMID 38898209, 2024). "Thus, our results demonstrate a gut bacteria-driven inflammasome activation that leads to GSDMD activation and enhanced tumor development." (PMID 38898209, 2024). "We examined the expressions of miR-221-5p and GSDMD in tumor tissues and paired adjacent tissues from 30 CRC patients and found that miR-221-5p expression was significantly higher but GSDMD expression was considerably lower in tumor tissues than in paracancerous tissues." (PMID 39439418, 2024).
tumor (continued). "Tumor sections from animal models, stained for Ki67 and GSDMD, reinforce the hypothesis that loratadine hampers tumor proliferation by promoting pyroptosis." (PMID 38163866, 2024). "GSDMD is downregulated or silenced in some tumours but upregulated in other tumours." (PMID 39616223, 2024). "However, additional studies with other inflammasome stimuli are needed to determine the full repertoire of GSDMD functions in tumor-immune relationships." (PMID 39224600, 2024). "Researchers have hypothesized that combining anti-PD-1 therapy with a GSDMD inhibitor might be more effective in suppressing tumor growth than single treatments alone, as it could enhance cancer immunity." (PMID 39544286, 2024). "This suggests that therapeutically applied GSDMD acts as a tumor suppressor." (PMID 39737979, 2024). "Compared with normal tissues, GSDMA and GSDMD showed higher expression levels in tumor stage 1." (PMID 39607202, 2024). "In addition, GSDMD-induced pyroptosis of antigen-presenting cells in tumor microenvironments impairs antigen presentation in response to anti-PD-L1 treatment." (PMID 39717896, 2024). "It is also unknown if inflammasome/GSDMD signaling is activated in the tumor, and if so, in which cells is the pathway activated, and how does such activation impacts the fate of these cells." (PMID 38898209, 2024). "The results showed that in tumor samples, GSDMD expression was positively correlated with the level of CD8+ T-cell markers in The Cancer Genome Atlas (TCGA) cohorts, and that GSDMD was upregulated in activated CD8+ T cells, while its deficiency would reduce the cytolytic ability of CD8+ T cells." (PMID 38553639, 2024). "Interestingly, GSDMD suppresses the cGAS-driven type I interferon response by depleting intracellular K+, and can, in this manner, promote tumor progression." (PMID 39224600, 2024). "However, IL-12 significantly enhanced the antitumor effects of NT GSDMD-induced pyroptosis and extensive control of tumor growth." (PMID 39737979, 2024). "Ablation of GSDMD reduced the number of tumor cells that harbor aggregated CHMP2A and CHMP4B." (PMID 38898209, 2024). "This suggests a supportive role for GSDMD in the tumor-killing effect of CD8+ T cells." (PMID 38066523, 2023). "Similar to our study, macrophage gasdermin-D plays a role in the tumor microenvironment." (PMID 37449203, 2023). "Since the NLRP3 inflammasome can be formed and activated by DAMPs, PLK2-induced DAMPs release could also be important for GSDMD pathway activation in USP18 depleted tumor environment in vivo." (PMID 36646704, 2023). "A combination system of a ruthenium (II) polypyridyl complex and Taxol could activate the pyroptosis key molecules of caspase‐1 and GSDMD to trigger caspase‐1/GSDMD‐mediated pyroptosis of A549 tumor cells for enhanced anticancer therapeutic effect." (PMID 37125240, 2023). "K-M survival analysis showed that GSDMD knockdown tumor-bearing mice had prolonged survival." (PMID 37371484, 2023). "Indeed, many researchers have found a host of chemicals that induce GSDMD-dependent pyroptosis of tumor cells through various mechanisms." (PMID 36932407, 2023). "Besides, anti-CD19 CAR-T therapy is demonstrated to induce GSDMD-mediated cell pyroptosis in B cell-derived tumor cells." (PMID 37095455, 2023). "Herein, targeted activation of TMEM173 in leukemic cells may induce GSDMD-dependent pyroptosis and reduce the tumor burden of B-ALL." (PMID 37095455, 2023). "The tumor volume was significantly smaller in the GSDMD knockdown group than that in the NC group." (PMID 37371484, 2023). "It is plausible that certain subclones within a tumor possess specific alterations or dependencies on GSDMD-mediated pyroptosis, which could contribute to the observed variability in disease outcomes." (PMID 38002346, 2023). "Luteolin inhibits tumor growth by inducing pyroptosis via caspase-1/GSDMD signaling." (PMID 36925932, 2023).